SMARCA4 (SWI/SNF related BAF chromatin remodeling complex subunit ATPase 4)
Diseases named in the same sentence as SMARCA4 in open-access papers (continued):
Sharing a sentence is not in itself a finding about the gene and the disease.
sarcomatoid carcinoma (6 papers, 2023 to 2025). A malignant epithelial neoplasm characterized by the presence of spindle cells and anaplastic morphologic features. "This study provides a comprehensive description of two rare cases of primary gastric SMARCA4-deficient carcinosarcoma and sarcomatoid carcinoma." (PMID 41170461, 2025). "This study presents two cases of SMARCA4-deficient gastric tumors: one case of carcinosarcoma and one of sarcomatoid carcinoma." (PMID 41170461, 2025). "The SMARCA4-deficient sarcomatoid carcinoma is essentially a special type of epithelial-derived carcinoma, in which tumor cells undergo mesenchymal-like morphological transformation." (PMID 41170461, 2025). "In Case 2, the tumor cells exhibited positive staining for CK and Vimentin, negative staining for SMARCA4, and the patient was positive for SMARCA4-deficient sarcomatoid carcinoma." (PMID 41170461, 2025). "The clinicopathologic features of gastric SMARCA4-deficient carcinosarcoma and sarcomatoid carcinoma." (PMID 41170461, 2025). "The final diagnosis was SMARCA4-deficient sarcomatoid carcinoma; pT4N1M0." (PMID 41170461, 2025). "Gastric SMARCA4-deficient carcinosarcoma and sarcomatoid carcinoma are particularly rare." (PMID 41170461, 2025). "Gastric SMARCA4-deficient carcinosarcoma and sarcomatoid carcinoma are rare with poor prognosis." (PMID 41170461, 2025). "However, differentiation between SMARCA4-deficient NSCLC and SMARCA4-UT can be difficult or sometimes impossible in microscopic biopsies because of poor morphology, immunosignature abnormalities, or sarcomatoid carcinoma in the biopsied region." (PMID 37115343, 2023).
colitis (5 papers, 2019 to 2024). Inflammation of the colon. "We found that Rag1−/−Smarca4ΔILC3 mice developed spontaneous colitis at 6–8 weeks of age, which was caused by enhanced production of GM-CSF from Brg1-deficient ILC3s." (PMID 32612160, 2021). "Since the deficiency of Brg1 was restricted to ILC3s in Rag1−/−Smarca4ΔILC3 mice, we reasoned that the colitis was caused by the pathogenicity of Brg1-deficient ILC3s." (PMID 32612160, 2021). "In contrast, the overexpression of BRG1 promoted T-bet-mediated suppression of GM-CSF in ILC3s, thereby ameliorating colitis in Rag1-/-Smarca4ΔILC3 mice." (PMID 36776858, 2023). "Blockade of GM-CSF ameliorates colitis in Rag1−/−Smarca4ΔILC3 mice, suggesting that the suppression of GM-CSF production from ILC3s by Brg1 serves as a critical mechanism for Brg1 to restrain intestinal inflammation." (PMID 32612160, 2021). "Notably, we observed no signs of colitis in Smarca4ΔILC3 mice by the age of 8 weeks as indicated by similar level of neutrophil infiltration, in spite of increased T-cell activation probably due to defective function of Tregs in the absence of Brg1." (PMID 32612160, 2021).
coronary artery disease (5 papers, 2017 to 2024). "Used multiple comparison, eight tests were performed, a significance level was P < 0.0063(0.05/8) based on Bonferroni correction, we found that rs12232780 in SMARCA4 gene influence the risk of Coronary heart disease." (PMID 28055962, 2017). "In our study, we found four genes with single nucleotide variants (SNVs) associated with coronary artery disease—HNF1A, LOX, SMAD3, and SMARCA4, and one gene, EBF1, with a SNV associated with carotid intima media thickness for the gens in significant modules." (PMID 35925965, 2022). "At present, there are many researches about the association between SMARCA4 and ZC3HC1 and coronary heart disease." (PMID 31507094, 2019). "SMARCA4 (OMIM: 603254) and ZC3HC1 (OMIM: 603254) are high‐risk genes for coronary heart disease." (PMID 31507094, 2019).
endometrioid carcinoma (5 papers, 2020 to 2022). "These tumors arise from endometrioid carcinomas, most commonly in a MMR-deficient (MMRd) background, by acquiring the following mutually exclusive alterations in the undifferentiated component: the co-mutation of ARID1B/ARID1A, SMARCA4 (BRG1) or SMARCB1 (INI1)." (PMID 35053578, 2022). "IHC staining of 6 EC cases (5 endometrioid carcinoma and 1 carcinosarcoma) with DICER1 hotspot mutations only identified ARID1A loss in one endometrioid carcinoma case, but neither SMARCA4 nor ARID1B was lost in any of the 6 cases." (PMID 33052929, 2020).
large cell neuroendocrine carcinoma (5 papers, 2021 to 2025). A usually aggressive carcinoma composed of large malignant cells which display neuroendocrine characteristics. "In contrast to SMARCB1-deficient carcinomas, and because of their cell morphology and immunophenotype, most SMARCA4-deficient tumors have been initially misclassified as small or large cell neuroendocrine carcinomas and, less frequently, as SNUC or teratocarcinosarcoma." (PMID 35307773, 2022). "SMARCA4-deficient large cell neuroendocrine carcinoma (SD-LCNEC) is particularly rare." (PMID 40661782, 2025). "Thoracic SMARCA4-UT is a recognized mimic of SCLC, and 23% of SMARCA4-UT in a recent series were initially diagnosed as small cell or large cell neuroendocrine carcinoma." (PMID 38180245, 2024).
microphthalmia (5 papers, 2010 to 2026). Congenital or developmental anomaly in which the eyeballs are abnormally small. "Through pangenomic analyses (whole-exome or whole-genome sequencing), we identified loss-of-function variants in SMARCA4 in three unrelated individuals with microphthalmia and/or coloboma." (PMID 41568967, 2026). "Eye abnormalities have been reported in CSS individuals including subjects with SMARCA4 variants, and they include severe myopia, strabismus, microphthalmia, and spherophakia." (PMID 30973214, 2019). "In addition, our case supports the dual role of chromatin remodellers in developmental disorders and cancer, as well as the involvement of SMARCA4 in microphthalmia, confirming previous findings in mouse models and the DECIPHER database." (PMID 28608987, 2017). "Taken together, these findings suggest that microphthalmia might be considered to be the result of SMARCA4 deregulation." (PMID 28608987, 2017).
mucinous adenocarcinoma (5 papers, 2022 to 2025). An invasive adenocarcinoma composed of malignant glandular cells which contain intracytoplasmic mucin. "In conclusion, a subset of HNF4α-positive adenocarcinomas, such as mucinous adenocarcinomas with gastrointestinal differentiation, are TTF-1-negative and SMARCA4 retained, often showing KRAS mutations." (PMID 38710944, 2025). "All cases of mucinous, enteric, and colloid adenocarcinoma were HNF4α-positive, TTF-1-negative, and SMARCA4 retained, and showed a high frequency of KRAS mutations (10/18, 55.6%) and no EGFR mutations (0/18, 0%)." (PMID 38710944, 2025). "The high expression of NOTCH3 and SMARCA4 indicates that the patients with colorectal adenocarcinoma are more likely to differentiate into mucinous adenocarcinoma." (PMID 35900231, 2022). "In our study, among the 90 mucinous adenocarcinoma cases, the deletion ratios of SMARCA4, SMARCA2, and ARID1A subunits were 6.7%, 5.6%, and 4.5%, respectively." (PMID 35289322, 2022). "Moreover, TTF-1-negative and HNF4α-positive non-mucinous adenocarcinomas showed wild-type EGFR and frequent SMARCA4 loss, and tended to show a high-grade solid morphology and very poor prognosis." (PMID 38710944, 2025). "Although HNF4α-positive grade 3 non-mucinous adenocarcinomas frequently showed the loss of SMARCA4 (2/6, 33%), it was not identified as a poor prognostic factor (Online Resource 6a)." (PMID 38710944, 2025). "In addition, all cases in the variant group retained SMARCA4 expression, but in the non-mucinous group, loss of SMARCA4 was detected in 3 of the 15 cases (20%), much more frequently than in HNF4α-negative non-mucinous adenocarcinomas (3/208, 1.4%)." (PMID 38710944, 2025). "Herein, we found that HNF4α-positive non-mucinous adenocarcinomas frequently showed loss of SMARCA4 (3/15, 20%), much more frequently than in mucinous, enteric, and colloid adenocarcinomas (0/18, 0%), and HNF4α-negative non-mucinous adenocarcinomas (3/208, 1.4%)." (PMID 38710944, 2025). "In addition, some conventional non-mucinous adenocarcinomas are HNF4α-positive, which include not only TRU-type adenocarcinomas that are double-positive for TTF-1 and HNF4α but also non-TRU-type poorly differentiated (grade 3) adenocarcinomas with frequent loss of SMARCA4 expression." (PMID 38710944, 2025). "HNF4α-positive non-mucinous adenocarcinomas included TRU-type and non-TRU-type cases; the latter tended to exhibit the high-grade phenotype with frequent loss of SMARCA4, and A549 was a representative cell line." (PMID 38710944, 2025).
renal cell carcinoma (5 papers, 2013 to 2025). "Herein, we present the first reported case of SMARCA4-deficient renal cell carcinoma (RCC) in an adult, marked by rapid clinical progression, prominent sarcomatoid and rhabdomyoblastic differentiation, and resistance to standard systemic therapies." (PMID 41312169, 2025). "We report the first documented case of SMARCA4-deficient renal cell carcinoma (RCC) in an adult (pT3aN1M1, Stage IV), characterized by sarcomatoid and rhabdomyoblastic differentiation, aggressive clinical behavior, and resistance to standard systemic therapies." (PMID 41312169, 2025). "The upregulation of the oncogene Pttg1 in Smarca4-deficient kidneys may shed new light on therapeutic strategies for renal cell carcinoma resulting from SWI/SNF complex deficiency." (PMID 37727504, 2023).
retinoblastoma (5 papers, 2015 to 2023). A malignant tumor that originates in the nuclear layer of the retina. "Here we explore the role of Brg1 (Smarca4) in retinal development and retinoblastoma in mice using molecular and cellular approaches." (PMID 26628093, 2015).
rhabdoid tumor predisposition syndrome 2 (5 papers, 2018 to 2024). Any familial rhabdoid tumor in which the cause of the disease is a mutation in the SMARCA4 gene. "Germline truncating SMARCA4 mutations cause a very rare tumor predisposition syndrome called Rhabdoid Tumor Predisposition Syndrome 2 (RTPS2; OMIM 613325), which is characterized by the early occurrence of small-cell carcinomas of the ovary hypercalcemic type (SCCOHT) or rhabdoid brain tumors." (PMID 30123105, 2018).
serous ovarian cancer (5 papers, 2021 to 2025). "To help unbiasedly assess the potential roles of SWI/SNF genes in modulating cisplatin responses, we performed a pooled CRISPR knockout screen targeting 496 epigenetic modifiers in OVCAR4, a SMARCA4/2-proficient high-grade serous ovarian carcinoma (HGSC) cell line." (PMID 34518526, 2021).
adrenocortical carcinoma (4 papers, 2021 to 2024). "We also used the “pathological stage plot” module of GEPIA2 to observe the correlation between SMARCA4 expression and the pathological stages of cancers, including adrenocortical carcinoma (ACC), BLCA, CESC, COAD, KICH, LUAD, pancreatic adenocarcinoma (PAAD), and THCA (all p< 0.05)." (PMID 34675941, 2021). "While one might consider the possibility of primary adrenal SMARCA4-deficient undifferentiated tumors, comprehensive genomic characterization and immunohistochemical feature of adrenocortical carcinomas have not revealed alterations in the SMARCA4 gene." (PMID 39723373, 2024).
autism spectrum disorder (4 papers, 2019 to 2022). A spectrum of developmental disorders that includes autism, and Asperger syndrome. "SMARCA4 has been associated with MIA-related autism spectrum disorder, and the nuclear factor kappa B subunit 1 (NFKB1) enrichment is aligned with the low-level chronic inflammation and enhanced response to an inflammatory stimulus in a knockout mouse model." (PMID 36672818, 2022). "Second, mutations of SMARCA4/Brm, a subunit of the SWI/SNF chromatin‐remodeling complex that regulates higher order chromatin structure and gene expression, have been linked to multiple neurological and psychiatric disorders including autism spectrum disorders and schizophrenia." (PMID 32749068, 2020).
carcinoid (4 papers, 2016 to 2025). "In addition, a mutation in the chromatin-remodeling SMARCA4 gene was identified in the adenocarcinoma component, frequently associated with pure carcinoid histology." (PMID 34926584, 2021). "Four additional somatic mutations were detected in the DDR2 (p.Arg806Ter), CDK6 (p.Thr107Ser), and SMARCA4 gene (p.Arg1135Gln) were identified in the adenocarcinoma component, whereas no specific mutations were identified in the carcinoid component." (PMID 34926584, 2021).
diffuse large B-cell lymphoma (4 papers, 2020 to 2024). "Among BAF subunits, ARID1A, ARID1B, and SMARCA4 are each mutated in ~10% of Diffuse Large B-Cell Lymphomas (DLBCL), which are thought to originate from malignant transformation of germinal center B cells." (PMID 38313292, 2024).
endometrial stromal sarcomas (4 papers, 2018 to 2025). "At the molecular level, endometrial stromal sarcomas often have no SMARCA4 deletion mutation." (PMID 37194064, 2023).
esophageal adenocarcinoma (4 papers, 2016 to 2024). A malignant tumor with glandular differentiation arising predominantly from Barrett mucosa in the lower third of the esophagus. "Though adenocarcinomas of esophagus and GE junction are frequently associated with Barret esophagus in the western world, the relationship of Barrett esophagus and the development of SMARCA4-UT is still unknown." (PMID 38497146, 2024). "Almost nothing is known about the other familiar members of the SWI/SNF complexes, SMARCA2 (BRM), SMARCA4 (BRG1) and SMARCB1 (INI1), in oesophageal adenocarcinoma (EAC)." (PMID 31906887, 2020). "During esophageal adenocarcinoma (EAC) development, somatic mutations of ARID1A and SMARCA4 are already present in benign metaplastic never-dysplastic Barrett's esophagus (NDBE)." (PMID 26812616, 2016).
gastric tumors (4 papers, 2016 to 2025). "It elaborates on their histological similarities and differences and further explores potential therapeutic approaches for SMARCA4-deficient gastric tumors." (PMID 41170461, 2025).
granulosa cell tumor (4 papers, 2019 to 2023). A slow-growing, malignant tumor, characterize by the presence of granulosa-like cells and Call-Exner bodies, that is almost always found in the ovary. "It is worth noting that COV434 cells, which were formerly classified as a juvenile granulosa cell tumor, have now been reclassified as SCCOHT, based on its SMARCA4 mutation and lack of SMARCA2 expression." (PMID 37535222, 2023). "The six non-SCCOHT tumours that demonstrated loss of SMARCA4 were immature teratoma (N = 1), desmoplastic round cell tumour (N = 1), PNET (N = 1) and adult granulosa cell tumour (N = 3)." (PMID 31844183, 2020).
intestinal cancer (4 papers, 2014 to 2024). "It is estimated that >20% of human cancers contain mutations in at least one BAF subunit, and protein expression of the catalytic subunit BRG1 (encoded by the SMARCA4 gene) is lost in >40% of brain, liver, kidney, and intestinal cancers." (PMID 38427725, 2024).
meningioma (4 papers, 2016 to 2023). A generally slow growing tumor attached to the dura mater. "Even more rarely, a SMARCA4 mutation has been reported in one anaplastic meningioma." (PMID 31470906, 2019). "In another study of 255 meningiomas, including 63 WHO grade 1, 173 grade 2, and 19 grade 3 meningiomas, the authors found ARID1A, SMARCA4, and SMARCB1 mutations in 17.3, 3.5, and 5.1% of samples, respectively." (PMID 37173979, 2023).
mesenchymal tumors (4 papers, 2021 to 2025). "CD34 is useful to distinguish CCS from Epithelioid neoplasms with SMARCB1 and SMARCA4 deficiency or Mesenchymal tumors with NTRK fusions which are positive for CD34." (PMID 33478436, 2021). "SWI/SNF complex-deficient carcinomas and mesenchymal tumors commonly share a discohesive epithelioid or rhabdoid morphology and this should guide the use of markers such as INI1 (SMARCB1) and BRG1 (SMARCA4) in the diagnostic work-up." (PMID 35864317, 2022). "As highlighted by Reference, carcinomas and mesenchymal tumors with SWI/SNF dysfunction frequently exhibit a discohesive epithelioid or rhabdoid phenotype, necessitating a targeted immunohistochemical evaluation of INI-1 (SMARCB1) and BRG1 (SMARCA4) during diagnostic workup." (PMID 40291911, 2025).
multiple myeloma (4 papers, 2009 to 2025). "Importantly, their case involved a patient with plasmacytic myeloma, who also exhibited INI-1 deficiency with SMARCA4 retention." (PMID 40291911, 2025). "Three other genes were also down-regulated (SMARCA4, BAZ2A and SMARCC2): SMARCA4 is a drug target candidates in hyperdiploid multiple myeloma; BAZ2A is a novel nucleolar chromatin remodeling machine, and SMARCC2 was among the top discriminating genes in the good prognosis subgroup of MLL." (PMID 19761576, 2009).
non-Hodgkin lymphoma (4 papers, 2020 to 2023). Distinct from Hodgkin lymphoma both morphologically and biologically, non-Hodgkin lymphoma (NHL) is characterized by the absence of Reed-Sternberg cells, can occur at any age, and usually presents as a localized or generalized lymphadenopathy associated with fever and weight loss. "Among SWI/SNF mutations, those in SMARCA4 are the most enriched in BL compared to other non-Hodgkin lymphomas." (PMID 36810086, 2023).
osteosarcoma (4 papers, 2009 to 2025). A usually aggressive malignant bone-forming mesenchymal neoplasm, predominantly affecting adolescents and young adults. "Three PRMTs (i.e., PRMT1, PRMT4/CARM1 and PRMT5) have each been shown to control vitamin D3-dependent transcription in osteosarcoma cells via interactions with SRC-1/NCOA1, whereas PRMT5 binds to the SWI/SNF component BRG1/SMARCA4 in different cell types." (PMID 37593409, 2023).
pancreatic adenocarcinoma (4 papers, 2013 to 2022). "Some studies have found that SMARCA4 is highly expressed in pancreatic adenocarcinoma and participates in many processes, such as cancer cell growth and proliferation." (PMID 36339709, 2022). "In Logsdon’s dataset, the transcription levels of SMARCA4 were significantly higher in patients with pancreatic adenocarcinoma, with a fold change of 2.257 and a P value of 7.16E−4." (PMID 34315468, 2021).
renal Rhabdoid Tumors (4 papers, 2015 to 2025). "Originally recognized as a distinct entity following cytogenetic identification of monosomy 22 in renal Rhabdoid Tumors, AT/RT now encompasses CNS tumors characterized by SMARCB1 (INI-1) or SMARCA4 (BRG-1) alterations within the SWI/SNF chromatin-remodeling complex." (PMID 41374972, 2025).
schizophrenia (4 papers, 2012 to 2020). A major psychotic disorder characterized by abnormalities in the perception or expression of reality. "REST can regulate the SMARCA4 gene and is linked to schizophrenia." (PMID 32039697, 2019). "We found dysregulation of multiple transcripts whose human orthologs are associated with BPD and other psychiatric disorders including schizophrenia and ADHD, including: Epor, Smarca4, Cmklr1, Cat, Tac1, Npsr1, Fhit, and P2rx7." (PMID 22675514, 2012).
thymoma (4 papers, 2021 to 2024). A neoplasm arising from the epithelial cells of the thymus. "SMARCA4-deficient cancers may be confused with “thymomas with anaplasia” that can also show defective keratin expression but retain SMARCA4 expression (own observation)." (PMID 33674910, 2021). "Genes involved in histone modification (BAP1, 13%; SETD2, 11%; ASXL1, 4%), chromatin remodelling (SMARCA4, 4%), and DNA methylation (DNMT3A, 7%; TET2, 4%; WT1, 4%) were frequently mutated in thymic carcinomas, but not thymomas." (PMID 35884448, 2022). "In a recent study, nine out of thirty nine mutated genes (23%) were involved in epigenetic regulation, with 34% of TCs exhibiting recurrent mutations in seven of them (BAP1, ASXL1, SETD2, SMARCA4, DNMT3A, TET2, and WT1), an observation which was not present for thymomas." (PMID 38338833, 2024).